IL10 (interleukin 10)
Diseases named in the same sentence as IL10 in open-access papers (continued):
Sharing a sentence is not in itself a finding about the gene and the disease.
cystic fibrosis (16 papers, 2006 to 2024). Autosomal recessive disorder caused by pathogenic variants in the CFTR gene (cystic fibrosis transmembrane conductance regulator), which encodes a chloride and bicarbonate channel expressed in epithelial cells, and follow the diagnosis criteria. "Additionally, high serum levels of IL-10 in patients with cystic fibrosis are associated with Aspergillus colonization and ABPA53." (PMID 30237437, 2018). "Consistent with mouse findings, human anti-Sa antibodies as well as anti-pseudomonal antibodies from cystic fibrosis subjects (high IL-10) are hypersialylated, compared with anti–Streptococcus pyogenes and pseudomonal antibodies from normal individuals." (PMID 39680460, 2024). "For instance, children with cystic fibrosis show increased TNF-α levels counterbalanced by simultaneous synthesis of IL-10." (PMID 31500172, 2019). "After induced inflammation, cystic fibrosis mice combined exaggerated cellular infiltration and lower anti-inflammatory interleukin-10 production." (PMID 17064416, 2006). "Interestingly, peripheral blood mononuclear cells from cystic fibrosis patients release a higher level of IL-10 compared with healthy subjects, and IL-10 suppressed the subjects’ T cell response to P. aeruginosa." (PMID 39680460, 2024). "Studies on cystic fibrosis revealed that the levels of proinflammatory cytokines including IL-1, TNF, IL-6 and IL-8 are higher in CF patients while level of IL-10 is lower comparing to healthy individuals." (PMID 35139898, 2022). "Since the two halophiles induced IL-10 by human DCs their effect may be anti-inflammatory, which is consistent with halotherapy having a beneficial effect for asthmatics, patients with chronic bronchitis, chronic obstructive bronchopneumopathy and cystic fibrosis." (PMID 35720372, 2022). "Antibodies from cystic fibrosis subjects are also nonfunctional, and there is a concurrent induction of high IL-10 levels from cystic fibrosis peripheral blood mononuclear cells compared with cells from normal subjects." (PMID 39680460, 2024). "Ralstonia, isolated from cystic fibrosis patients, were negatively correlated with indices of antioxidant capacity (POD, T-AOC, and GSH), digestive enzymic activities (trypsin, LPS, and AKP), and anti-inflammatory capacity (IL-10 and CD209)." (PMID 35844501, 2022). "Moreover, a clinical trial (phase II NTC 02649751) was investigating the function of roscovitine in the chronic inflammatory lung disease cystic fibrosis by monitoring pro- (TNF-α) and anti-inflammatory (IL-10) parameters, among others." (PMID 34502552, 2021). "In a non-oral infection model, AAV-mediated gene transfer of IL-10 reduced airway inflammation in mice infected with Pseudomonas aeruginosa, the major pathogen in cystic fibrosis." (PMID 23577057, 2013). "IL10 was elevated significantly (p = 0.045) at the conditioning/sham time-point in patients with obstructive CF compared to those with obstructive non-cystic fibrosis and restrictive disease (p = 0.045)." (PMID 26820896, 2016).
Encephalopathy (16 papers, 2017 to 2026). Encephalopathy is a term that means brain disease, damage, or malfunction. "Elevated levels of interleukins IL-6 and IL-10 have been implicated in influenza-associated encephalopathy and correlate with disease severity." (PMID 40416295, 2025). "Univariate logistic regression identified influenza virus infection, prodromal-to-encephalopathy interval ≤24 h, tracheal intubation, Glasgow Coma Scale (GCS) <5, prolonged APTT, and elevated PCT and IL-10 as risk factors for mortality." (PMID 41815731, 2026). "Patients with IL-10 ≥29.1 pg/ml had higher intensive care unit admission (P<0.0001), SFTS-associated encephalopathy (P = 0.0178), lower viral clearance (P<0.0001) within the first 14 days following symptom onset, and reduced 28-day survival (P = 0.0007)." (PMID 41601653, 2026). "Fourth, a patient with norovirus-associated encephalopathy showed elevated concentrations of cerebrospinal fluid interleukin-6, interleukin-10, interferon-γ, and tumor necrosis factor-α suggesting that her encephalopathy was related to hypercytokinemia." (PMID 37477790, 2023). "We also observed a trend with severity; IL-10 levels were higher in infants with moderate (p = 0.046) and severe (p = 0.009) encephalopathy compared to infants with mild encephalopathy." (PMID 33674741, 2022). "Conversely, the persistent correlation between Sarnat scores and this index suggested a disproportionate IL-10 response with worse encephalopathy." (PMID 34795631, 2021). "Previous studies reported increased serum and cerebrospinal fluid concentrations of IL-1β, IL-6, IL-10, and TNF-α, as well as increased transcription of their coding genes in patients with influenza-associated encephalopathy and FS." (PMID 34300253, 2021). "However, when specifically compared to HC, patients with encephalopathy had significantly increased levels of IP-10 in serum, and NfL levels in serum and CSF, and lower levels of IL-10 in CSF." (PMID 35479062, 2022). "Elevations of IL-6, IL-10, and sTNFR1, but not IL-2, IL-4, and IFNγ,γwere associated with poor outcome in influenza-associated encephalopathy, with serum levels of cytokines usually higher than in the CSF." (PMID 33391257, 2020). "Higher Sarnat score (worse encephalopathy) correlated with lower VEGF during the first 24 h of life (DOL 0) and higher tau, GFAP, and IL-10 throughout the first week of life." (PMID 34795631, 2021).
gastric ulcer (16 papers, 2013 to 2025). An ulcerated lesion in the mucosal surface of the stomach. "Atractylodes exerts anti-inflammatory activity in gastric ulcer rats by down-regulating NF-κB and IL-1β while up-regulating IL-10 and IκBα." (PMID 41036224, 2025). "The induction of IL-10 is consistent with previous reports where agarwood oil was shown to increase IL-10 levels in in vivo mice models of intestinal injury and gastric ulcer." (PMID 36839377, 2023). "Pretreatment with AAEs significantly reduced the proinflammatory cytokine levels of IL-1β and IL-6 and enhanced the anti-inflammatory cytokine IL-10 in the gastric ulcer mice, suggesting that they provide protection against the inflammation of gastric ulcer." (PMID 34580595, 2021). "Several studies show a positive correlation between the severity of gastric ulcer and the increase in pro-inflammatory cytokines (IL-1β, IL-6, and TNF-α), associated with a reduction in anti-inflammatory cytokines (IL-10), influencing inflammatory scores." (PMID 33233494, 2020). "Oral treatment with L-menthol decreased tumor necrosis factor-α (TNF-α), interleukin-6 (IL-6) levels, and increased interleukin-10 (IL-10) level in the rat model of gastric ulcers." (PMID 31827561, 2019). "Effect of menthol (50 mg/kg) on the levels of TNF-α, IL-6 and IL-10 cytokines in rat stomachs with ethanol-induced gastric ulcers after treatment with vehicle, carbenoxolone (100 mg/kg) or menthol (50 mg/kg)." (PMID 24466200, 2014). "The pro-inflammatory cytokines TNF-α and IL-1β have been shown to play an important role in the pathogenesis of gastric ulcer by initiating an early inflammatory process, while the regulatory cytokine IL-10 is known to attenuate TNF-α production." (PMID 23484048, 2013). "Accordingly, oral TA treatment of mice with ethanol-induced and ethanol/HCl-induced gastric ulcers exhibited gastroprotective effects, which were associated with a decrease in TNF-α, IL-1β and IL-6 protein levels and an increase in IL-10 protein levels in gastric tissue." (PMID 40427543, 2025). "In addition, gastric ulcer can promote the expression of upstream IL-8, IL-10, and IL-10 in chronic infection to inhibit the occurrence of adaptive immune responses and weaken the clearance effect on antigen." (PMID 32775468, 2020). "The impaired healing of gastric ulcer in diabetic rats was associated with suppressed tissue expression endothelial cell markers (i.e. eNOS and peNOS), enhanced pro-inflammatory reactions (i.e. IL-1β, IL-6 and myeloperoxidase activity) and reduced regenerative activity (i.e. MMP-2, IL-10 and cAMP)." (PMID 29095895, 2017). "Diosmin showed gastroprotection (100 mg/kg, p.o.)against ethanol-induced gastric ulcers in rats, suppressed gastric inflammation, reducing TNF-α and NF-kB expression and restored levels of anti-inflammatory interleukin-10 (IL-10)." (PMID 33233494, 2020). "Dehydrocostus lactone could relieve ethanol-induced gastric ulcers in mice, which was considered to be related to the decrease in TNF-α, COX-2, and MDA and the increase in IL-10 and PCNA." (PMID 37109624, 2023).
hemophagocytic lymphohistiocytosis (16 papers, 2016 to 2025). "Our previous study also proved that IL-10 is a risk factor for early death in secondary hemophagocytic syndrome cases with severe cytokine networks." (PMID 35463642, 2022). "Among 20 patients with secondary Hemophagocytic lymphohistiocytosis (sHLH), levels of IL-10 and TNF-α were significantly elevated compared to other MS cases without sHLH (P < 0.001 and P= 0.025, respectively)." (PMID 41176307, 2025). "SARS-CoV-2 increases interferon gamma, tumor necrosis factor-α, macrophage inflammatory protein-1 alpha, IL-2, IL-6, IL-7, IL-10, in patients, that show a form of secondary hemophagocytic lymphohistiocytosis or macrophage activation syndrome (sHLH/MAS)." (PMID 33494816, 2021). "A study on hemophagocytic lymphohistiocytosis (HL), a prototypical hyperinflammatory disease, suggests that IL-18 and IL-10 may collectively promote the onset of a hyperinflammatory state." (PMID 37112918, 2023). "Interleukin-10 (IL-10) is an independent factor for predicting adverse outcomes in pediatric patients with hemophagocytic lymphohistiocytosis (HLH)." (PMID 34348761, 2021). "Tocilizumab is able to attenuate the levels of IFN‐γ, IL10, and IL2, and treat refractory hemophagocytic lymphohistiocytosis (HLH) with expansion of cytotoxic T and NK cells." (PMID 37193304, 2023). "Moreover, it may elevate other proinflammatory cytokines, including IL-6, IL-8 and IL-10, generated by other bystander immune cells, resulting in even more severe hyperactive immune disorders, hemophagocytic lymphohistiocytosis (HLH) and macrophage activation syndrome (MAS)." (PMID 35432345, 2022). "Trend of change in cytokine levels (IL-10, IFN-γ, IL-6) (pg/mL), neutrophil count (×109/L), hemoglobin level (g/L), and platelet count (×109/L) since the onset of hemophagocytic lymphohistiocytosis." (PMID 34964741, 2021).
listeriosis (16 papers, 2012 to 2023). A bacterial infection caused by Listeria monocytogenes. "Since IL-10 produced by NK cells has been recently shown to enhance susceptibility of mice to Listeria infection we analyzed whether ADAP-deficiency would affect the capacity of NK cells to produce IL-10." (PMID 32038647, 2019). "As an underlying mechanism for the detrimental role of NK cells in listeriosis the authors uncovered that NK cells responding to Lm infection acquire the ability to produce the immunosuppressive cytokine IL-10." (PMID 32038647, 2019). "Moreover, IL-10 high levels were also reported to increase in listeriosis of aged mice with high bacterial loads." (PMID 27965668, 2016). "In addition, IL-10 expression level was also significantly lower in the spleens of Hvem-/- mice than that in WT mice upon Listeria infection." (PMID 26245828, 2015). "Furthermore, impaired IFN-I expression in Hvem-/- mice leads to diminished IL-10 expression and higher IFNGR expression, which provide further information how HVEM deficiency confers the host resistant to Listeria infection." (PMID 26245828, 2015). "Finally, the reduced production of innate IL-12p70 and increased production of IL-10 by neonatal innate cells upon stimulation would be expected to lead to suboptimal activation of CD8+ T cells and thus increased susceptibility to listeriosis." (PMID 23653659, 2013). "Hence, they are likely to be related to the IL-10-producing effector T cells found in experimental Toxoplasma gondii and Listeria monocytogenes infection and Plasmodium infection." (PMID 22911108, 2012). "Therefore, high levels of Th2 cytokines (IL-6 or IL-10) seemed related with severe listeriosis." (PMID 27965668, 2016). "Here, we report that GAPDH1–22 epitopes can activate MoDC of listeriosis patients with cancer receiving chemotherapy to release high levels TNF-α while low production of IL-6 and IL-10, a clear Th1 cytokine pattern." (PMID 27965668, 2016). "We also observed that GAPDH1–22-activated MoDC from listeriosis patients with cancer released high levels of TNF-α while low levels of IL-6 and IL-10, suggesting a shifting toward Th1 pattern." (PMID 27965668, 2016). "The synergistic effect of functionally abnormal IL-12p40 allele and high levels of IL-10 production in response to IFNγ may help explain how BTBR mice can both express higher IL-12(p40) and IL-12(p70) than their C57 counterparts, but also be more susceptible to Listeriosis." (PMID 24062633, 2013). "Production of Th1 cytokines MCP-1, TNF-α and IFN-γ and lack of production of Th2 cytokines such as IL-6 and IL-10, which are responsible for exaggerated inflammatory reactions and putative autoimmune responses in listeriosis, are features that are also relevant for protective DC vaccine vectors." (PMID 24600592, 2014). "GNP-GAPDH1-22 formulated with Advax, while showing listeriosis protection in brains (2-3 CFU/mL), failed to reduce liver LMWT (400 CFU/ml) and produced anti-GAPDH1-22 antibodies, while produced high IL-10 levels." (PMID 28903312, 2017). "Since patients with listeriosis have failed to produce anti-LLO antibodies, we focused on GNP-GAPDH1-22 nanovaccines, selecting the adjuvant DIO-1 for the vaccine formulation, because it induces IL-12p40 and fails to produce IL-10, avoiding disproportionate inflammation in the brain." (PMID 28903312, 2017).
liver failure (16 papers, 2012 to 2025). A liver disease characterized by the liver losing or has lost all of its function. "T-cell-mediated immunity is known to be reduced in patients with liver failure, especially in those with severe alcoholic hepatitis, who exhibit high levels of interleukin-10 and low production of interferon-γ." (PMID 40459718, 2025). "IL-10 secreted by transplanted MSCs activated the mammalian target of rapamycin (mTOR) pathway and thereby enhanced mitochondrial function as well as correct abnormal lipid metabolism in treating post-hepatectomy liver failure." (PMID 39497124, 2024). "Our study found that MSCs secreted IL-10 to alleviate liver failure after hepatectomy, and inhibition of IL-10 secretion could reverse the therapeutic effect of MSCs." (PMID 33479191, 2021). "IL-10, as an anti-inflammatory and cytoprotective cytokine, was only detected in peripheral blood, where higher levels in OLR indicated increased systemic inflammation and, together with IL-6 and MCP1, suggested an increased risk of postoperative liver failure." (PMID 41006707, 2025). "Simultaneously, interleukin (IL)-10, an anti-inflammatory cytokine that inhibits Th1 and Th2 immune responses, was also found to increase, suggesting that IL-10+ T cells could induce immune tolerance, preventing the progression of mild liver injury to liver failure." (PMID 37575717, 2023). "The levels of cytokines, such as IL-10, IL-2, IL-4, IL-6, IFN-γ, and GM-CSF in PBC patients who developed liver failure, were significantly reduced, and the difference in IL-2 between the two groups was statistically significant (P=0.028)." (PMID 36159788, 2022). "In addition, IL-10 has also been reported to be correlated with chronic progression of HBV infection and predict the prognosis of liver failure." (PMID 28390195, 2017). "In addition, our results suggest that negative regulatory treatment (corticosteroids or IL-10) should be started at the CHB acute exacerbation phase and not at the time of diagnosing liver failure." (PMID 25147572, 2014).
prediabetes (16 papers, 2013 to 2026). "We concluded that Hs-CRP, IgE, IL-4, IL-10, and tryptase were positively associated with prediabetes or T2DM." (PMID 27478850, 2016). "In conclusion, circulating inflammatory mediators, hs-CRP, IgE, IL-4, IL-10, and tryptase, were positively associated with prediabetes or T2DM." (PMID 27478850, 2016). "Could plasmatic IL-10 levels be used as a marker to detect the possible risk of prediabetes in an H. pylori-infected patient?" (PMID 33013895, 2020). "This suggests that plasma levels of IL-10 reflect the load of bacterial colonization and the intensity of inflammatory process in the gastric mucosa, which reinforces the possibility of serum IL-10 being used as a risk marker for prediabetes in H. pylori-infected patients." (PMID 33013895, 2020). "Another study demonstrated elevated serum TNF-α levels and reduced serum IL-10 levels in patients with prediabetes and patients with T2DM and PDN compared with controls without DM." (PMID 39408723, 2024). "In contrast, the levels of IL-10, an anti-inflammatory molecule, were diminished in the prediabetes and T2D groups." (PMID 38834984, 2024). "CRP and IL-10 were also discriminatory between prediabetes and T2DM, indicating their potential efficiency as biomarkers alongside BGL for the transition from prediabetes to T2DM disease status." (PMID 37383391, 2023). "Between the three study groups, serum IL-10 was significantly different, and the score followed the order: controls < prediabetes−IR < prediabetes+IR." (PMID 34099024, 2021). "The immune system molecules, particularly interleukin (IL)-6 and IL-10, are other important molecules that mediate the inflammatory response and need more study in prediabetes." (PMID 34099024, 2021). "Prediabetes+IR can be predicted by the increased levels of IL-10, βEP, and EM2 and by the combination of IL-10 and EM2/KOR with good sensitivity and specificity." (PMID 34099024, 2021). "Serum IL-10 was significantly different among the three study groups (F = 9.362, df = 2/175, p < 0.001), and the score followed the order: prediabetes+IR > prediabetes−IR > controls." (PMID 34099024, 2021). "The first regression analysis showed that prediabetes was best predicted by increased levels of IL-10, zLnβEP, and zLnEM2 (χ2 = 38.122, df = 7, p < 0.001, Nagelkerke = 0.480) with an accuracy of 76.7%, sensitivity of 85.0%, and specificity of 75.6%." (PMID 34099024, 2021). "Prediabetes+IR can be predicted using the increased rates of the IL-10, βEP, and EM2 mixture and a mixture of IL-10 and EM2/KOR with strong sensitivity and specificity." (PMID 34099024, 2021). "Regardless of the lack of statistical significance, there were slightly lower levels of interleukin-10 and interferon-γ in the group with prediabetes or T2DM at the third year and the sixth year after ETV therapy, respectively." (PMID 31698809, 2019). "Our data showed increased levels of CRP, IL-4, IL-10, and tryptase in prediabetes subjects and increased levels of CRP, IL-4, and IL-10 in T2DM subjects compared with normal glucose subjects." (PMID 27478850, 2016). "However, serum concentrations of IL-10 were reduced in T2D and prediabetes patients compared with controls." (PMID 38834984, 2024). "Additionally, the prediabetes and T2D groups had higher concentrations of proinflammatory molecules such as IL-6, IL-1β and IL-8, and lower concentrations of IL-10, an anti-inflammatory cytokine, than controls (P < 0.001)." (PMID 38834984, 2024). "However, it is essential to investigate other inflammatory factors, such as IL-10, TNF-α, and adipokines, which are implicated in prediabetes." (PMID 38004306, 2023). "However, vitamin D3 supplementation tends to decrease the ratio of IL-6/IL-10 compared with the prediabetes group." (PMID 37324274, 2023). "Furthermore, the IL-10, zLnβEP, zLnMOR, and zLnEM2 in the prediabetes subgroups were significantly higher than those in the control group." (PMID 34099024, 2021).